COX20 (cytochrome c oxidase assembly factor COX20)
Description:
Essential for the assembly of the mitochondrial respiratory chain complex IV (CIV), also known as cytochrome c oxidase. Acts as a chaperone in the early steps of cytochrome c oxidase subunit II (MT-CO2/COX2) maturation, stabilizing the newly synthesized protein and presenting it to metallochaperones SCO1/2 which in turn facilitates the incorporation of the mature MT-CO2/COX2 into the assembling CIV holoenzyme.
Synonyms: FAM36A; FLJ43269; MC4DN11
Tractability: Antibody: UniProt predicts a signal peptide or a membrane-spanning region. PROTAC: ubiquitination databases record sites on it; its protein half-life has been measured.
Gene: Protein-coding gene on chromosome 1 (244,835,616 to 244,845,480, forward strand). Ensembl gene ENSG00000203667.
Subcellular location: Mitochondrion inner membrane
Subcellular location (Human Protein Atlas): Mitochondria
Pathways (Reactome):
Metabolism: Complex IV assembly
Gene Ontology:
Molecular function: protein binding
Biological process: mitochondrial respiratory chain complex IV assembly
Cellular component: mitochondrial inner membrane; mitochondrion
Genetic constraint (gnomAD): Loss-of-function variants: 2 observed, 1.29 expected, observed/expected ratio (o/e) 1.55, 90% interval 0.47 to 1.93. That is too few expected variants to judge how well the gene tolerates losing a copy. Missense variants: 65 observed, 39.93 expected, observed/expected ratio (o/e) 1.63, 90% interval 1.33 to 1.92. Synonymous variants: 24 observed, 15.66 expected, observed/expected ratio (o/e) 1.53, 90% interval 1.1 to 1.92.
Gene-disease validity (ClinGen):
ClinGen rates the evidence that COX20 causes each of these diseases.
mitochondrial disease (autosomal recessive): Definitive.
Homologues: Orthologues: chimpanzee COX20 (97% identical), macaque COX20 (91% identical), mouse Cox20 (81% identical), guinea pig COX20 (80% identical), rat LOC120096563 (70% identical), dog COX20 (53% identical).
Diseases named in the same sentence as COX20 in open-access papers:
COX20 is named in the same sentence as 31 diseases in open-access papers, as found by Europe PMC text mining. Sharing a sentence is not in itself a finding about the gene and the disease. The quoted sentences say what the papers report.
Ataxia (5 papers, 2015 to 2025). Ataxia refers to impaired coordination of voluntary muscle movement. "A review of the literature indicates that the primary clinical manifestations of COX20-associated disease include ataxia, gait disturbances, and areflexia (or hyporeflexia)." (PMID 41010014, 2025). "In another case, we packaged two cDNA isoforms of COX20, deficiency of which causes ataxia and muscle hypotonia in children." (PMID 38558570, 2024). "Here we report a Chinese child with COX20 deficiency, who manifested developmental delay, ataxia, hypotonia, dysarthria, strabismus and visual impairment." (PMID 37095481, 2023). "The most frequent clinical features of COX20-associated mitochondrial disorder includes sensory neuropathy, ataxia, dysarthria, hypotonia, dystonia, and ophthalmoplegia." (PMID 37095481, 2023). "Nevertheless, COX20-related disease represents a clinical continuum, frequently including combination of ataxia, dysarthria, spinal cord atrophy, and peripheral motor–sensory neuropathy." (PMID 41010014, 2025). "Previous studies showed that COX20 deficiency (MIM #619054) is involved in neurological disorders presenting with muscle hypotonia, ataxia, dysarthria, and axonal neuropathy." (PMID 35651336, 2022). "COX20 might be considered as a potential gene for the early-onset ataxia and the axonal sensory neuropathy." (PMID 37095481, 2023). "Compound heterozygous mutations (c.41A > G and c.222G > T, NM_198076) in the COX20 gene were identified in two siblings from a non-consanguineous family presenting with ataxia, dystonia, ophthalmoplegia, dysarthria, and sensory-dominant neuropathy." (PMID 35651336, 2022). "In our patient, the search for repeat expansions in common spinocerebellar ataxia genes, as well as a gene panel for hereditary neuropathies, which did not include the COX20 gene, revealed no significant findings." (PMID 41010014, 2025). "The patient exhibited progressive ataxia, pyramidal signs, and peripheral neuropathy, accompanied by cervical spinal cord atrophy on spinal cord MRI and lower leg muscle fat infiltration on muscle MRI, an imaging feature not previously emphasized in COX20-related disease." (PMID 41010014, 2025).
Dystonia (3 papers, 2022 to 2025). An abnormally increased muscular tone that causes fixed abnormal postures. "Patients with COX20 variants showed clinical symptoms during childhood and gradually developed additional signs such as dystonia, dysarthria, and sensory-dominant neuropathy." (PMID 35651336, 2022). "There have been reports suggesting that mutations in the SURF1, COX20, and SCO2 genes, which are involved in the assembly of COX along with COA7, can result in a decrease in the activity of MRC complex IV, leading to dystonia or parkinsonism." (PMID 37750949, 2024).
epilepsy (2 papers, 2017 to 2019). A brain disorder characterized by episodes of abnormally increased neuronal discharge resulting in transient episodes of sensory or motor neurological dysfunction, or psychic dysfunction. "The minimal critical region for epilepsy was narrow and included HNRNPU and COX20, which is a gene that tolerates haploinsufficiency." (PMID 28283832, 2017). "The HNRNPU (heterogeneous nuclear ribonucleoprotein U) and the FAM36A (family with sequence similarity 36, also known as COX20—cytochrome c oxidase assembly factor) genes, were proposed as good candidates for the epilepsy and ID phenotype within the 1q43-q44 microdeletion syndrome." (PMID 30853971, 2019). "Thus, heterozygous deletions of COX20 are unlikely to be responsible for the epilepsy phenotype." (PMID 28283832, 2017).
glioma (2 papers, 2023 to 2024). A benign or malignant brain and spinal cord tumor that arises from glial cells (astrocytes, oligodendrocytes, ependymal cells). "In conclusion, the three mitochondria-related signatures by UQCRB, CMC1, and COX20 have the ability to predict OS in gliomas." (PMID 37091853, 2023). "CMC1, COX20, and UQCRB are other mitochondrial genes specifically involved in the prognosis of glioma." (PMID 39012280, 2024).
heart failure (1 paper, 2020). Inability of the heart to pump blood at an adequate rate to meet tissue metabolic requirements. "We have provided further compelling evidence suggesting that some of our prioritized rank-ordered list of proteins, including FAM162A, MCT1, and COX20 are cardiac enriched, localized within subcellular compartments, and may play a role in the progression of heart failure." (PMID 33262348, 2020). "In an attempt to establish the link between altered expression and human heart diseases, we performed immunoblot analysis of FAM162A, MCT1, and COX20 to investigate protein levels in human hearts from patients with clinical DCM and ICM, the two most common etiologies of heart failure." (PMID 33262348, 2020).
intellectual disabilities (1 paper, 2020). "We also did not observe the severe cognitive or intellectual disabilities of COX20-related diseases typically reported in literature." (PMID 32999401, 2020).
ischemic cardiomyopathies (1 paper, 2020). "FAM162A, MCT1, and COX20 were expressed differentially at the transcriptomic and proteomic levels in multiple models of mouse and human heart diseases and may represent potential diagnostic and therapeutic targets for human dilated and ischemic cardiomyopathies." (PMID 33262348, 2020).
ophthalmoplegia (1 paper, 2022). Weakness or paralysis of at least one of the muscles controlling the movement of the eye. "Our study broadens the clinical phenotypes of ophthalmoplegia and visual failure associated with COX20 variants." (PMID 35651336, 2022). "Our results broaden the clinical phenotypes of patients with COX20 variants showing ophthalmoplegia and visual failure." (PMID 35651336, 2022). "This is the first description of ophthalmoplegia and visual failure associated with COX20 variants." (PMID 35651336, 2022). "However, ophthalmoplegia and visual failure associated with COX20 mutation have not been examined previously." (PMID 35651336, 2022).
cardiovascular diseases (1 paper, 2020). "To assess for any correlation to cardiac disease, we performed a query of publicly available GEO RNA-Seq datasets containing data for human and mouse cardiovascular diseases to determine expression levels of FAM162A, MCT1, and COX20." (PMID 33262348, 2020).
heart diseases (1 paper, 2020). "In addition to the phenotypic analysis using the mouse genome informatics data, no known human mutations of FAM162A, MCT1, and COX20 have been linked to classical human heart diseases." (PMID 33262348, 2020).
movement disorder (1 paper, 2022). Neurological conditions resulting in abnormal voluntary or involuntary movement, which may impact the speed, fluency, quality and ease of movement. "Early-onset complex movement disorders may be closely related to COX20 variants." (PMID 35651336, 2022).
COX20 also shares sentences with these, for which no sentence is quoted: cancer (2 papers); Areflexia (1); ataxia telangiectasia (1); atherosclerosis (1); axonal sensory neuropathy (1); encephalomyopathies (1); Friedreich ataxia (1); giant axonal neuropathy (1); Hyporeflexia (1); idiopathic cardiomyopathy (1); lung carcinoma (1); microcephaly (1); mitochondrial disease (1); neuropathy (1); Parkinsonism (1); peripheral neuropathy (1); schizophrenia (1); Spastic paraplegia (1); spinocerebellar ataxia type 2 (1); Strabismus (1).